ICOSLG (inducible T cell costimulator ligand)
Description:
Ligand for the T-cell-specific cell surface receptor ICOS. Acts as a costimulatory signal for T-cell proliferation and cytokine secretion. Also induces B-cell proliferation and differentiation into plasma cells. Could play an important role in mediating local tissue responses to inflammatory conditions, as well as in modulating the secondary immune response by co-stimulating memory T-cell function (By similarity). In endothelial cells, required for proper neutrophil transmigration in response to chemoattractants, such as CXCL8/IL8 or N-formyl-methionyl peptides (fMLP).
Synonyms: B7-H2; B7RP-1; CD275; B7H2; B7RP1; ICOSL; KIAA0653; GL50; ICOS-L; B7h; IMD119; LICOS
Tractability: Antibody: a drug acting on it is in phase 2 or 3 trials; UniProt places it where antibodies can reach, with high confidence; its Gene Ontology location is reachable by antibodies, with high confidence; UniProt predicts a signal peptide or a membrane-spanning region. PROTAC: its protein half-life has been measured; a small molecule that binds it is known.
Gene: Protein-coding gene on chromosome 21 (44,215,382 to 44,241,446, reverse strand). Ensembl gene ENSG00000160223.
Subcellular location: Cell membrane; Cell membrane (Isoform 2)
Subcellular location (Human Protein Atlas): Plasma membrane; Vesicles
Pathways (Reactome):
Immune System: Co-stimulation by ICOS
Gene Ontology:
Molecular function: identical protein binding; protein binding; receptor ligand activity; signaling receptor binding
Biological process: T follicular helper cell differentiation; defense response; hyperosmotic response; positive regulation of activated T cell proliferation; regulation of cytokine production; signal transduction; T cell activation; T cell receptor signaling pathway
Cellular component: extracellular exosome; plasma membrane; external side of plasma membrane; membrane
Gene-disease validity (ClinGen):
ClinGen rates the evidence that ICOSLG causes each of these diseases.
combined immunodeficiency (autosomal recessive): Moderate. A broad classification of inherited disorders presenting at birth that affect both the cell-mediated and humoral aspects of the immune response.
Homologues: Orthologues: chimpanzee ICOSLG (93% identical), macaque ICOSLG (88% identical), dog ICOSLG (57% identical), rat Icoslg (51% identical), mouse Icosl (45% identical), tropical clawed frog icoslg (25% identical). Paralogues in human: CD276 (26% identical), BTN1A1 (22% identical), BTN2A2 (21% identical), BTN3A1 (21% identical), BTN2A1 (21% identical), BTN3A3 (21% identical), BTNL8 (21% identical), BTNL3 (20% identical), HHLA2 (19% identical), BTN3A2 (18% identical), BTNL9 (18% identical), BTNL2 (16% identical), and 3 more.
Diseases named in the same sentence as ICOSLG in open-access papers:
ICOSLG is named in the same sentence as 166 diseases in open-access papers, as found by Europe PMC text mining. Sharing a sentence is not in itself a finding about the gene and the disease. The quoted sentences say what the papers report.
breast carcinoma (36 papers, 2015 to 2025). "In contrast, studies on melanoma and breast cancer showed that ICOSLG expression on tumor cells promoted the expansion of regulatory T cells, and thereby immune evasion." (PMID 38067332, 2023). "Patients in the low-risk category of pancreatic cancer may have comparable resistance mechanisms to those seen in breast cancer, where ICOSLG has been shown to be a possible biomarker for the development of trastuzumab resistance." (PMID 36359832, 2022). "Breast cancer patients with high EZH2, ICOSLG expression and low DPP4 expresssion had potentially stronger ability to release sICOSL, and thus a significant adverse overall survival." (PMID 40708008, 2025). "OPN triggers the inducible T cell costimulator ligand (ICOSL) and thereby promotes angiogenesis and cell migration in breast cancer." (PMID 39062100, 2024). "In breast cancer, the activation of ICOS and ICOSLG is closely related to the accumulation of Tregs cells and DCs, and is also an indispensable key factor in the activation of Tregs cells." (PMID 37842091, 2023). "Rb-loss reduces several ‘hallmarks’ of immune response in mouse models, and its deficiency correlates with the induction of PVR, CD274 and several other IC modulators, including ICOSLG and TNFRSF12A in human breast cancer." (PMID 37230983, 2023).
melanoma (31 papers, 2016 to 2026). A malignant, usually aggressive tumor composed of atypical, neoplastic melanocytes. "In conclusion, our results show that the clinical advantage of concomitant treatment with cetirizine during checkpoint inhibition in patients with malignant melanoma is associated with high expression of ICOSLG." (PMID 39596506, 2024). "In melanoma, ICOSLG is linked with increasing numbers of regulatory T-cells (Treg), but has not previously been described in HPV(+) HNSCC." (PMID 27462861, 2016). "In conclusion, our results show that the clinical advantage of concomitant treatment with cetirizine during checkpoint inhibition in patients with malignant melanoma is associated with high ICOSLG expression, which could predict the response to immune checkpoint inhibitor blockade." (PMID 39596506, 2024). "In melanoma, the high expression of ICOSLG on tumor cells is closely related to the decrease of patient survival." (PMID 37842091, 2023). "We have also analyzed the expression of costimulatory receptors CD86 and ICOSLG on TAM from B16-F10 melanoma and CT26 colon carcinoma models." (PMID 35503656, 2022). "Firstly, we compared the expression levels of 43 immune-stimulator genes between FGFR Mut and FGFR Wt melanoma, with the majority of genes expressing higher in FGFR Mut melanoma, especially ICOSLG and TNFSF13 (P < 0.05)." (PMID 36426352, 2022). "Detailed analysis of tumor-infiltrating myeloid cells from melanoma patients revealed that the CD206+ Macro_C1QC subset also expressed high levels of HLA-A (MHC I) and CD86, as well as ICOSLG, and low levels of CD274, as we had observed in our cross-presenting CD206+ M2a macrophages." (PMID 35503656, 2022). "It was shown in both ex vivo patient samples and in that a humanized melanoma mouse model that pDC in melanoma are directed toward a TH2 promoting phenotype by induction of the molecules OX-40L (TNFSF4) and ICOSL (inducible T cell costimulator ligand), which then drive tumor progression." (PMID 29276510, 2017). "Interestingly, when a stimulatory ICOS antibody was used in combination with anti-CTLA-4, there was a significant improvement in tumor rejection in both melanoma and colon cancer mouse models, suggesting that HPV(+) tumors expressing high levels of ICOSLG may respond better to anti-CTLA-4 therapy." (PMID 27462861, 2016).
systemic lupus erythematosus (19 papers, 2013 to 2026). An autoimmune multi-organ disease typically associated with vasculopathy and autoantibody production. "In this study, we evaluated the gene polymorphisms of the ligand genes corresponding co-stimulatory system that were expressed on antigen-presenting cells (CD80, CD86, ICOSLG, and PDL1) from 60 systemic lupus erythematosus (SLE) patients and 60 healthy controls." (PMID 38361527, 2023).
glioma (14 papers, 2014 to 2025). A benign or malignant brain and spinal cord tumor that arises from glial cells (astrocytes, oligodendrocytes, ependymal cells). "Upregulation of ICOSLG (in mesenchymal glioma stem cells) in glioblastoma tissue was associated with poor prognosis in patients." (PMID 40724825, 2025). "The IGLoS signature consists of six immune infiltration‐related genes associated with the survival of diffuse patients with glioma, which are CCL19, ICOSLG, IL11, PTGES, TNFAIP3, and TRAF3IP3." (PMID 40714831, 2025). "Previous reports indicated that TRPM2, ICOSLG are potential oncogenes in glioma." (PMID 35521558, 2022). "In the Gusu in‐house dataset consisting of 24 patients with glioma, TRAF3IP3, TNFAIP3, ICOSLG, IL11, and PTGES, showed a trend of increasing expression with increasing tumor grade, whereas CCL19 was not." (PMID 40714831, 2025). "Next, we used the LASSO regression to further select six key regulators consisting of CCL19, ICOSLG, IL11, PTGES, TNFAIP3, and TRAF3IP3, and they were named the Immune Glioma Survival Signature (IGLoS signature)." (PMID 40714831, 2025). "ALKBH5 expression showed positive association with ICP receptors such as TNFRSF14, CD40, CD96 and CD200R1, and ICP ligands such as PDCD1LG2, CD70, TNFSF14, ICOSLG and CD274 in glioma tissues." (PMID 35444654, 2022). "Glioma prognosis was correlated to immune checkpoints LGALS9, PVR, TNFSF9 and ICOSLG." (PMID 40777122, 2025). "In addition, our Circos plots also demonstrated the robust interaction between ICOS and ICOSLG in both LGG and GBM, further confirming the pro-oncogenic role of the ICOS/ICOSLG pathway in gliomas." (PMID 36276141, 2022).
asthma (9 papers, 2015 to 2026). "In a study of an asthma model, a four-week treadmill exercise program led to a reduction of co-stimulatory molecules, CD80, CD86, and inducible T-cell costimulator ligand (ICOSL), in cDCs located in the lymph nodes that drained from the affected areas, and an increase in ICOSL expression in pDCs." (PMID 37841264, 2023).
autoimmune disease (9 papers, 2006 to 2024). A disorder resulting from loss of function or tissue destruction of an organ or multiple organs, arising from humoral or cellular immune responses of the individual to their own tissue constituents. "Both ICOSLG and HLA-DRA are known to be involved in immunity, and considering that MS is a type of autoimmune disease, perhaps this relationship explains the mechanism of rs4819388 and rs3177928 in MS and indicates that ICOSLG, HLA-DRA may be associated with MS." (PMID 32117605, 2020).
glioblastoma (9 papers, 2021 to 2026). The most malignant astrocytic tumor (WHO grade IV). "It has been implicated ICOSLG as as a predictor and therapeutic target in acute lymphoblastic leukemia, and can promote the progression of glioblastoma by mediating the regulatory T-cell expansion." (PMID 37605192, 2023). "ICOSLG is expressed on GBM tumor cells, its upregulation being associated with the presence of glioblastoma stem cells and IL-10-producing T cells as well as the mesenchymal phenotype." (PMID 40895574, 2025). "Through investigation of expression status and molecule function of the ligand of ICOS (ICOSLG) in glioblastomas, they concluded that ICOSL, via conjugation with ICOS, was associated with more malignancy of glioblastoma." (PMID 36276141, 2022). "In addition, in glioblastoma, high expression of ICOSLG promotes the proliferation of CD4+ T cells by stimulating the secretion of IL-10, but knocking out ICOSLG of tumor cells increases the number of CD8+ T cells." (PMID 37842091, 2023).
atherosclerosis (7 papers, 2018 to 2024). A disease characterized by the build-up of fatty material and calcium deposition in the arterial wall resulting in partial or complete occlusion of the arterial lumen.
colorectal cancer (5 papers, 2017 to 2026). A primary or metastatic malignant neoplasm that affects the colon or rectum. "The high expression of ICOSLG on CD4+ T cells is positively correlated with advanced TNM stage in colorectal cancer (CRC)." (PMID 37842091, 2023). "For instance, patients with colorectal cancer more commonly had high expression of GZMB and ICOSLG (Relative risk [RR]: 1.87 and 1.46, respectively)." (PMID 37553332, 2023). "In colorectal cancer, studies have found that increased expression of ICOSLG in CD8+ T cells leads to poor prognosis in patients." (PMID 37842091, 2023). "In the TISCH2 database, single-cell sequencing analysis showed that the mRNA expression of ICOSLG was significantly higher in TILs in liver hepatocellular carcinoma, colorectal cancer, and head and neck squamous cell carcinoma." (PMID 37842091, 2023).
gastric cancer (4 papers, 2020 to 2025). A primary or metastatic malignant neoplasm involving the stomach. "It has been reported that high expression of ICOSLG promotes immunosuppression and tumor escape in gastric cancer by down-regulating function of Th1 type cells." (PMID 37842091, 2023). "Results showed higher staining of CD86 (118/157, 75%), ICOSLG (122/157, 77%), B7-H3 (138/157, 88%), B7-H7 (138/157, 88%), and B7-DC (104/157, 66%) and overall lower staining of CD80 and B7-H6 in gastric cancer tissues." (PMID 32025206, 2020). "In addition, in gastric cancer, co-stimulation of ICOS and ICOSLG can lead to the activation of Tregs cells and may be associated with poor prognosis of patients." (PMID 37842091, 2023).
lung carcinoma (4 papers, 2021 to 2023). "Immune-related plasma proteins in lung cancer patients were quantified, and Fas ligand (FASLG) and inducible T-cell co-stimulator ligand (ICOSLG) were demonstrated to be associated with response and survival." (PMID 38067332, 2023).
myeloma (4 papers, 2012 to 2026). "In myeloma, tumor cells with high expression of ICOSLG have stronger proliferation ability and can activate ICOS-ICOSLG pathway to inhibit tumor immune response." (PMID 37842091, 2023).
cervical cancer (3 papers, 2015 to 2023). A primary or metastatic malignant neoplasm involving the cervix. "Genes PFDN4, CASP1, PLCE1, ICOSLG, GADD45G, SMARCA2, and TSPO are located in different chromosomes, and there are reports for changes in each one of these chromosomes in cervix cancer, for examples the reader is refer to:." (PMID 26388997, 2015). "However, HMGB1 secretion during cervical cancer progression impairs the antiviral response by inhibiting IFNα secretion and increasing ICOSL (Inducible T Cell Costimulator Ligand) expression by plasmacytoid dendritic cells (pDCs)." (PMID 38138866, 2023).
head and neck cancer (2 papers, 2019 to 2022). A primary or metastatic malignant neoplasm affecting the head and neck. "RT-qPCR was performed to investigate gene expression and the correlation between AP001056.1 and ICOSLG in matched tumor-free and tumor samples from 12 patients with squamous cell carcinoma of the oral tongue (SCCOT), the most common head and neck cancer subtype." (PMID 30862109, 2019).
lymph node metastasis (2 papers, 2019 to 2023). "The results showed that in OSCC patients, the expression of ICOSLG was not significantly correlated with gender, age, and differentiation, but the high expression of ICOSLG in TCs (ICOSLGTCs) and TILs (ICOSLGTILs) was associated with higher risk of lymph node metastasis and advanced TNM stage." (PMID 37842091, 2023). "Lymph node metastasis and high expression of ICOSLG in TCs and TILs were significantly different in OS and MFS, but not independent prognostic indicators of oral squamous cell carcinoma." (PMID 37842091, 2023).
oral squamous cell carcinoma (2 papers, 2023 to 2024). "In this study, we investigated the expression pattern of ICOSLG in oral squamous cell carcinoma, including tumor cells (TCs), cancer-associated fibroblasts (CAFs) and tumor infiltrating lymphocytes (TILs)." (PMID 37842091, 2023).
prostate carcinoma (2 papers, 2017 to 2021). A carcinoma that arises from epithelial cells of the prostate gland. "By performing a screen for proteins in pre-operative and post-operative serum from men with high-risk prostate cancer, we identified CASP8, MSLN, FGFBP1, ICOSLG, TIE2, and S100A4 proteins as candidate biomarkers for high-risk prostate cancer." (PMID 33828176, 2021). "MSLN, FGFBP1, ICOSLG, and TIE2 were also elevated in sera from patients with BPH, suggesting that MSLN, FGFBP1, ICOSLG, and TIE2 were not specific for high-risk prostate cancer." (PMID 33828176, 2021).
Sepsis (2 papers, 2022 to 2025). Sepsis is defined as life-threatening organ dysfunction caused by a dysregulated host response to infection. "In the high-risk group, LAIR1 was also elevated, as were immunosuppressive genes CD276, ICOSLG, and PDCD1LG2, which is consistent with immunosuppressive status in sepsis patients and further indicates that poor prognosis in patients with sepsis may be closely linked to immunosuppression." (PMID 40504881, 2025).
Alexander disease (1 paper, 2022). Alexander disease (AxD) is a rare neurodegenerative disorder of the astrocytes comprised of two clinical forms: AxD Type I and Type II manifesting with various degrees of macrocephaly, spasticity, ataxia and seizures and leading to psychomotor regression and death. "Furthermore, in a previous collaboration, we detected upregulation of ICOSLG at the transcriptional level in both post-mortem brain samples and hiPSC-derived astrocytes from patients with Alexander Disease, a neurodegenerative disease caused by mutations in GFAP." (PMID 35592112, 2022).
chronic obstructive pulmonary disease (1 paper, 2019). A chronic and progressive lung disorder characterized by the loss of elasticity of the bronchial tree and the air sacs, destruction of the air sacs wall, thickening of the bronchial wall, and mucous accumulation in the bronchial tree. "Human pulmonary cDC2s mediated IL-10 producing Treg, which suppressed chronic obstructive pulmonary disease (COPD), via IL-10, IL-27 and inducible T cell costimulator ligand (ICOSL)." (PMID 31640263, 2019).
colitis (1 paper, 2024). Inflammation of the colon. "In comparison, patients with high ICOSLG expression had an increased risk of arthralgia (33.9% vs. 8.3%, p = 0.02), colitis (22.6% vs. 0, p = 0.01), pancreatitis (17.7% vs. 0, p = 0.03), and skin reactions (50% vs. 16.7%, p = 0.01)." (PMID 39596506, 2024). "Additionally, treatment with cetirizine is associated with an increased risk of colitis, while high ICOSLG expression predicts a higher risk of colitis, arthralgia, pancreatitis, and skin reactions." (PMID 39596506, 2024). "Patients treated with cetirizine had a higher risk of colitis than the overall population (25.5% vs. 5.1%, p = 0.02), independent of ICOSLG expression." (PMID 39596506, 2024).
endometriosis (1 paper, 2022). The growth of functional endometrial tissue in anatomic sites outside the uterine body. "In endometriosis, PEA technology identified seven proteins up-regulated (IL-6, IL-8, CCL 19, SCF, VEGF-D, IL-6RA, MIA9) and ten proteins down-regulated (ICOSLG, EGFR, SELE, ErbB2/HER2, IL-6RA, VEGFR-2, Flt3L, CXCL10, HE4, FR-alpha)." (PMID 36009404, 2022).
esophageal squamous cell carcinoma (1 paper, 2023). Esophageal squamous cell carcinoma (ESCC) is a type of esophageal carcinoma (EC) that can affect any part of the esophagus, but is usually located in the upper or middle third. "In esophageal squamous cell carcinoma, inhibition of ICOSLG can reduce the number of Tregs cells, thereby improving the effect of tumor immunotherapy." (PMID 37842091, 2023).
helminth infections (1 paper, 2021). "In MS patients with helminth infections, there is a compensatory abundance of IL-10-producing B cells through a mechanism that is largely dependent on the Inducible T cell costimulator ligand (ICOSLG)-pathway and not on the CD40, CD80 or CD86 pathways." (PMID 34122439, 2021).
Hodgkins lymphoma (1 paper, 2010). A heterogeneous group of malignant lymphoid neoplasms of B-cell origin characterized histologically by the presence of Hodgkin and Reed-Sternberg (HRS) cells in the vast majority of cases. "Module II consists of miRNAs from the Hodgkin Lymphoma cell line, hsa-miR-17, hsa-miR-24, and ebv-miR-BART3, and genes from the "regulation of lymphocyte activation" category - CDKN2A and ICOSLG." (PMID 20465802, 2010).
inflammatory bowel disease (1 paper, 2023). A spectrum of small and large bowel inflammatory diseases of unknown etiology. "Co-localisation analyses across genetic effects on DNA methylation and 56 human traits identify 1520 co-localisations across 1325 unique CpGs and 34 phenotypes, including in disease-relevant genes, such as USP1 and DOCK7 (total cholesterol levels), and ICOSLG (inflammatory bowel disease)." (PMID 37525248, 2023).